EPCAM (epithelial cell adhesion molecule)
Diseases named in the same sentence as EPCAM in open-access papers (continued):
Sharing a sentence is not in itself a finding about the gene and the disease.
head and neck cancer (23 papers, 2007 to 2025). A primary or metastatic malignant neoplasm affecting the head and neck. "This has been done with the bispecific EpCAM/CD3ε binding antibody AMG 110, which has been linked to 89Zr and used to detect tumors in colorectal and head and neck cancer xenografts." (PMID 32041116, 2020). "Studies with tumour samples from head and neck cancer patients indicate that EpCAM can be aberrantly glycosylated on tumour cells." (PMID 17211480, 2007). "U Zangemeister-Wittke (Bern, Switzerland) reported on the development of an EpCAM-specific immunotoxin called Proxinium (4D5MOC31-ETA) that currently is in a pivotal phase II/III trial for local treatment of head & neck cancer." (PMID 17211480, 2007). "Furthermore, EPCAM knockdown in esophageal and head and neck carcinoma cells resulted in an increase in their migratory capacity following Vimentin expression." (PMID 34680248, 2021). "EpCAM was strongly glycosylated in 77% of cases of head and neck carcinomas studied (n=44)." (PMID 17622246, 2007). "Notably, a hyperglycosylation pattern was observed in head and neck carcinoma when compared with healthy EpCAM-positive epithelium." (PMID 17622246, 2007). "Therefore, a specific strategy such as targeting EpCAM could be beneficial in cancers such as CRC or head and neck cancer where both EpCAM and Wnt signaling components were highly expressed." (PMID 39010070, 2024). "A deimmunized bispecific targeted toxin (Pseudomonas enterotoxin) against EpCAM and CD133 showed efficacy against UMSCC-11B head and neck carcinoma in a xenograft murine model." (PMID 27650544, 2016). "EPCAM molecules derived from head and neck carcinomas are hyperglycosylated, while EPCAM from healthy head and neck tissues contains no or little N-glycosylation." (PMID 36639722, 2023). "Similarly, a completely humanized bispecific antibody targeting EpCAM and CD16 showed significant increase in ADCC, increased degranulation of NK cells with concomitant increase in IFN-g production against EpCAM positive prostate, breast, colon, and head and neck cancer cell lines." (PMID 30805309, 2019). "To explore whether these EpCAM+Vim+CD24+ cells in the stroma may in fact be non-tumour cell types, we analysed a published scRNAseq dataset for human head and neck cancer." (PMID 37975646, 2023).
lung adenocarcinoma (23 papers, 2012 to 2025). A carcinoma that arises from the lung and is characterized by the presence of malignant glandular epithelial cells. "EPCAM promotes proliferation, metastasis, and invasion of tumor cells, but overexpressed EPCAM is associated with a better prognosis in patients with adenocarcinoma of the lung, breast and gall bladder cancer, and squamous cell carcinoma of the esophagus." (PMID 36131343, 2022). "Among them, CRABP2, KAT2A, BIRC5, ABCC3, PLK1, IGHG1, and EPCAM were upregulated in lung adenocarcinoma samples, while FABP4 was downregulated in lung adenocarcinoma samples." (PMID 35909589, 2022). "We used flow cytometry to validate lung adenocarcinoma cells, normal epithelial cells, and macrophages with cell markers (EPCAM, FOLR1, and CD163)." (PMID 36249427, 2022). "The expression of AKR1C1, AKR1C2, AKR1C3, and AKR1C4 proteins, which was mainly overexpressed in lung adenocarcinoma (A549) cells and associated with drug resistance in NSCLC, was found in the A549 CD166 + EpCAM + CSC subpopulation." (PMID 33670440, 2021). "EPCAM is another progenitor cell marker that has been proposed as a potential therapeutic target for lung adenocarcinoma." (PMID 34439225, 2021). "This methodology used in our study allows us to identify almost every CTC by the epithelial adhesion molecule EpCAM, which has been shown to exhibit a high frequency of expression in most human cancers, and up to 80% expression in lung adenocarcinomas." (PMID 28938646, 2017). "Another example is the interaction between EpCAM and solitomab in lung adenocarcinoma." (PMID 40258059, 2025). "We hypothesize that lncCDH5-3:3 controls CDH1 and, as a consequence, EPCAM expression, which encodes EpCAM, one more protein involved in the regulation of EMT, thereby exerting an important influence on the progression of lung adenocarcinoma." (PMID 35159188, 2022). "We isolated putative lung CSCs from lung adenocarcinoma cells (A549 and H2170) and normal stem cells from normal bronchial epithelial cells (PHBEC) on the basis of positive expression of stem cell surface markers (CD166, CD44, and EpCAM) using fluorescence-activated cell sorting." (PMID 25881239, 2015).
congenital tufting enteropathy (22 papers, 2009 to 2026). "The organ/tissue with the strongest EpCAM expression is the colorectum, which develops congenital tufted enteropathy (CTE) due to EpCAM mutation in humans." (PMID 38791091, 2024). "Conversely, mutations in human SPINT2 were associated with congenital tufting enteropathy characterized by severe intestinal dysfunction with induced EpCAM cleavage and decreased claudin-7 expression that resulted in organoid rupture." (PMID 37830556, 2023). "EPCAM mutations have been associated with congenital tufting enteropathy, an autosomal recessive disease with a described incidence of 1 in 50,000–100,000 live births in Western Europe." (PMID 36422736, 2023). "Congenital tufting enteropathy (CTE) is a life-threatening intestinal disorder resulting from loss-of-function mutations in EPCAM and SPINT2." (PMID 37539662, 2023). "EpCAM deficiency causes congenital tufting enteropathy (CTE) which is considered as one kinds of very early onset inflammatory bowel disease (IBD)." (PMID 35493520, 2022). "In humans and mice, the most prominent feature of mutations in EpCAM is development of congenital tufting enteropathy (CTE)." (PMID 33525555, 2021). "A study of congenital tufting enteropathy patients demonstrated that some EpCAM germline mutations can alter cellular trafficking and localization of EpCAM protein to the cell surface." (PMID 33980181, 2021). "Humans with biallelic inactivating mutations in Epithelial Cell Adhesion Molecule (EpCAM) develop congenital tufting enteropathy (CTE)." (PMID 33525555, 2021). "Congenital tufting enteropathy (CTE) is a rare chronic diarrheal disease of infancy caused by mutations in epithelial cell adhesion molecule (EpCAM)." (PMID 32290509, 2020). "Congenital tufting enteropathy (CTE) is a rare disease that manifests as intractable diarrhea during the neonatal period which is associated with mutations of the epithelial cell adhesion molecule (EpCAM) gene." (PMID 32293360, 2020). "EpCAM deficiency causes congenital tufting enteropathy (CTE) in humans and a corresponding lethal condition in mice." (PMID 32781650, 2020). "For example, EpCAM mutations can cause congenital tufting enteropathy (CTE), in which abnormal actomyosin contractility at tricellular junctions causes extension of the apical domain and pathological tuft formation of the intestinal epithelium." (PMID 30304739, 2018). "Loss of EpCAM causes loss of Claudin-7 from the intestinal epithelium which is associated with congenital tufting enteropathy and loss of intestinal epithelial integrity in mice and humans." (PMID 30304739, 2018). "Congenital tufting enteropathy, a disorder caused by mutations in EpCAM, results in a serious clinical phenotype that is debilitating to children." (PMID 25482158, 2015). "Congenital tufting enteropathy (CTE) is a severe paediatric disease caused by a point mutation of EpCAM (Cys66Tyr)." (PMID 24009667, 2013). "Inactivating germ-line mutations of the human EPCAM/TROP1/TACSTD1 gene have been associated with congenital tufting enteropathy (CTE), a life-threatening intestinal dysplasia that manifests from birth." (PMID 23209569, 2012). "However, it is considered pathogenic with respect to Congenital Tufting Enteropathy which is an autosomal recessive condition associated with biallelic pathogenic variants in the EPCAM gene." (PMID 36421850, 2022). "Truncating and null mutations of EpCAM in humans and mice cause congenital tufting enteropathy (CTE), a severe diarrheal disorder characterized by epithelial dysplasia, compromised intestinal barrier, failure to thrive, and, in mice, post-natal demise within the first week of life." (PMID 32781650, 2020). "In humans, mutations in EpCAM cause congenital tufting enteropathy (CTE), a disease which is associated with loss of tight junction protein Claudin-7 and increased actomyosin contractility at epithelial cell-cell junctions leading to the disruption of intestinal epithelial integrity." (PMID 30304739, 2018).
congenital tufting enteropathy (continued). "EpCAM is highly expressed in ISCs,1 and most patients of congenital tufting enteropathy (CTE), caused by EpCAM mutations, die of intestinal failure." (PMID 39939830, 2025). "Congenital tufting enteropathy (CTE), also known as intestinal epithelial dysplasia (IED), is a rare autosomal recessive disorder due to EPCAM gene mutation." (PMID 36743443, 2023). "In the case of patient 6, however, the dual molecular diagnosis of homozygous pathogenic variants in EPCAM and BEST1 did not correspond to a hybrid phenotype because her only presentation was diarrhea as part of EPCAM-related tufting enteropathy (OMIM# 613217)." (PMID 38716412, 2024). "Similarly, recurrence risk was complicated in Patient 6 who was found to have in addition to the primary finding of EPCAM-related tufting enteropathy the unexpected finding of BEST1-related inherited retinal disease." (PMID 38716412, 2024). "Highlighted Article: Cleavage-resistant EpCAM does not prevent intestinal failure in the Spint2-deficient mouse model of congenital tufting enteropathy, challenging the current model of proteolysis-driven disease progression." (PMID 37539662, 2023). "Intrauterine demise or abnormal fertility has not been reported in families of patients with congenital tufting enteropathy, but it may be significant that null mutations in the gene encoding EpCAM, or mutations that resulted in truncated EpCAM protein, have not yet been identified in patients." (PMID 20046825, 2009).
glioma (22 papers, 2012 to 2026). A benign or malignant brain and spinal cord tumor that arises from glial cells (astrocytes, oligodendrocytes, ependymal cells). "Cultured ELISPOT assays clearly confirmed responses against individual minigenes from two pools targeted by T cells from subject ND2, one derived from epithelial adhesion molecule, EpCAM in pool #308, and another encoding a portion of glioma pathogenesis associated protein, GLIPR1 in pool #85." (PMID 22253836, 2012). "Potential glioma risk genes with a pathogenic GV most frequently played roles in cell adhesion (CTNND1, EPCAM), immune response (IFIH1, SAMHD1), and ion transport (SLC4A7, TRPM1)." (PMID 41546701, 2026). "Mechanistically, lncTCF7 enhances the self-renewal of glioma cells by increasing the expression of epithelial cell adhesion molecules (EpCAM)." (PMID 40248351, 2025). "EpCAM overexpression correlates with cell proliferation, Ki-67 expression, angiogenesis, and poor survival in high-grade gliomas." (PMID 40106404, 2025). "Three patients had EVs positives for CD326/EpCAM, a glycoprotein overexpressed in glioma cells, especially in grade IV gliomas." (PMID 40106404, 2025). "The research of Gu and colleagues showed that sEVs-EpCAM promoted glioma metastasis via targeting CD44 signaling molecules which are on the surface of glioma cells." (PMID 38951882, 2024). "Studies on gliomas have shown that EpCAM overexpression significantly correlates with microvessel density, which indicates the participation of this protein in angiogenesis." (PMID 35406725, 2022). "Indeed, in patients with gliomas, it has been reported that EpCAM overexpression correlates significantly with malignancy (WHO grades), proliferation (Ki67), angiogenesis, and prognosis." (PMID 26689993, 2016). "Conversely, LGR5− glioma cells showed low expression of CD133, CD44, CD90, CD24, and EpCAM, while the expression of CD90 remained unchanged in LGR5+ and LGR5− glioma cells." (PMID 30208924, 2018). "We found that LGR5+ glioma cells possessed considerably enhanced expression of CD133, CD44, CD90, CD24, and EpCAM." (PMID 30208924, 2018). "The expression levels of CD133, CD44, CD24, CD90 and EpCAM were examined in LGR5+ and LGR5− U251 and 8591 glioma cells by FCM." (PMID 30208924, 2018). "As glioma does not express the epithelial cell adhesion molecule (EpCAM) typical for carcinomas, standard EpCAM-based CTC isolation methods cannot be employed." (PMID 40285800, 2025). "For malignant astrocytoma, the challenges are more profound as most CTCs detection strategies rely on antibody-mediated capture targeting cell-surface expression of EpCAM, which is not present in glioma cells." (PMID 37525780, 2023). "Malignant glioma cells that have undergone EMT do not express EpCAM, which makes them undetectable using the Cell-Search approach." (PMID 37525780, 2023). "Several CSC markers have been reported in glioma, such as CD133, CD24, CD90, CD44 and EpCAM." (PMID 30208924, 2018). "However, gliomas do not express EpCAM, and hence less specific microfluidic techniques are being utilized for detection." (PMID 36425564, 2022). "However, the most prominent difference between central nervous system tumors and epidermal malignant tumors is the lack of EpCAM expression, which makes the detection of glioma CTCs challenging and requires other strategies." (PMID 34763698, 2021). "Moreover, another study also showed that the exosome EpCAM promotes the metastasis of glioma by targeting the CD44 signaling molecule on the surface of glioma cells; this exosome influenced the progression of glioma." (PMID 34722277, 2021). "While gliomas are EpCAM negative, the results regarding CK-positivity are less consistent." (PMID 31466397, 2019). "Moreover, tumor cells disseminated in cerebrospinal fluid (CSF) of extremely high-mortality glioma patients, who account for 70% of 22,500 annual new cases of brain tumors in the United States, do not express both EpCAM and CK." (PMID 26267323, 2015).
leukemia (22 papers, 2009 to 2025). A malignant (clonal) hematologic disorder, involving hematopoietic stem cells and characterized by the presence of primitive or atypical myeloid or lymphoid cells in the bone marrow and the blood. "Studies also showed that EpCAM was used as a novel target for the treatment of leukemia, and anti-EpCAM antibody depleted acute myeloid leukemia (AML) in a mouse model." (PMID 40017594, 2025). "Both aptamers exhibited high affinity for EpCAM+ CCA cells, with negligible binding to EpCAM- leukemia cells." (PMID 39513807, 2024). "In this paper, a kind of leukemia targeting MNPs was developed by immobilizing the epithelial cellular adhesion molecule (EpCAM) antibody on the surface of MNPs (EpCAM-MNPs)." (PMID 33916177, 2021). "EpCAM-MNPs can target and remove leukemia cells circulating in the bloodstream and were reported to decrease viability of human monocytic leukemia (THP1) cells by over 40%." (PMID 33916177, 2021). "In another study, it was found that EpCAM antibody can target EpCAM+ chemoresistant leukemia subpopulations after chemotherapy in a mouse model, suggesting EpCAM is a promising novel target for the treatment of leukemia." (PMID 30419852, 2018). "In leukemia, EpCAM was found to hinder immune surveillance by activating Wnt5B signaling." (PMID 36369033, 2022). "In acute myeloid leukemia, EpCAM+ leukemia cells show augmented chemoresistance and oncogenesis." (PMID 36428553, 2022). "Fluorescent images of carcinoma cells among cultured T lymphoblastoid leukemia cells stained with PE-labeled anti-cytokeratin monoclonal antibody or APC-labeled anti-EpCAM monoclonal antibody were obtained, and the merged image identified the doubly positive carcinoma cells." (PMID 22396762, 2012). "Moreover, in xenograft mouse models, the protective environment for leukemia in the bone marrow could be counteracted by EpCAM antibodies." (PMID 36369033, 2022). "To evaluate the aptamer binding specificity to EpCAM, we determined the binding of PLD01, PLD02, and EpDT3, an RNA aptamer that is known to target EpCAM, on either EpCAM-positive HuCCT1 CCA cells or EpCAM-negative HL60 leukemia cells." (PMID 39513807, 2024). "The elevated expression of EpCAM in ALL cases suggests that EpCAM, being a regulator of cell proliferation, has a role in leukemia progression, and that its protein might be a potential target for therapy." (PMID 36428553, 2022). "Several studies suggested that epithelial cell adhesion molecule (Ep-CAM) might be a marker reflecting the epithelial state of primary and systemic tumor cells, and the specific expression of Ep-CAM in leukemia cells could be used as an indicator to measure the metastasis of leukemia tumor cells." (PMID 37063276, 2023).
Pleural effusion (22 papers, 2010 to 2025). The presence of an excessive amount of fluid in the pleural cavity. "In our study, we found that the cancer cells in the pleural effusion exhibited the phenotype of circulating tumour cells (CTCs) and expressed metastatic markers such as Epithelial Cell Adhesion Molecule (EpCAM) and Tumour Associated Calcium Signal Transducer 2 (TACSTD2)." (PMID 38629624, 2024). "EpCAM-positive vesicles were detected in the plasma, ascites and pleural effusion of OC patients, as well as in conditioned media of OC cell lines." (PMID 37375854, 2023). "constructed recombinant oncolytic adenovirus-encoded EpCAM-targeted BiTEs (EnAd-SA-EpCAMBiTE and EnAd-CMV-EpCAMBiTE) and validated their antitumor efficacies in patients with pleural effusions and ascites." (PMID 36451817, 2022). "Primary cell lines were established from pleural effusion and double immunofluorescence staining samples for the epithelial markers EpCAM or cytokeratin, and the mesenchymal marker Vim was performed." (PMID 35199053, 2022). "Incubation for 7 days with solitomab significantly decreased the number of EpCAM-positive tumor cells in the freshly collected pleural effusion sample." (PMID 26474755, 2015). "In five out of seven cases a correspondence of EpCAM and CK expressions was observed between CTCs, and tumor cells in ascites or pleural effusion samples." (PMID 21595914, 2011). "EpCAM-CK+ cells could be found in pleural effusion specimens and in peripheral blood samples of patients with NSCLC." (PMID 21595914, 2011). "Finally, cell lines that exhibited a spindle-like morphology in culture, were derived from either pleural effusions or primary tumor tissues and were largely comprised of EpCAM-/CD24-/CD49f+ Mesenchymal cells (> 90%); thus, referred to as Mesenchymal lines." (PMID 20964822, 2010). "After processing, the purity of cancer cells identified in pleural effusion by CD45 and epithelial cell adhesion molecule antibodies in flow cytometry will be increased by 6 to 24 times." (PMID 34832761, 2021). "Similarly to EVs from serum, exosomes from BrCa pleural effusions contained ADAM10, CD9, and CD24 but also contained the epithelial cell adhesion molecule (EpCAM), a highly expressed protein on cancer cells." (PMID 26601108, 2015). "Importantly, EpCAM was not identified in cells purified from pleural effusions of patients with benign conditions, nor from cancer patients whose cytological examination was negative for malignancy." (PMID 40525275, 2025). "Enzymes and specific signaling proteins (EpCAM, EFGR, and survivin-2B) along with metalloproteinase ADAM10, heat-shock protein HSP70, and Annexin-1 can also be evidenced as general marker proteins detected in serum and pleural effusion-derived SEVs from BC cell lines or BC patients." (PMID 37108371, 2023).